TNF (tumor necrosis factor)
Diseases named in the same sentence as TNF in open-access papers (continued):
Sharing a sentence is not in itself a finding about the gene and the disease.
infection (continued). "The Salmonella counts, Activated Neutrophil, NET, TNF-α, HMGB-1, MDMI, and MDMII levels in the simulation sharply increased at the beginning of the infection but progressively decreased as the infection progressed." (PMID 27556404, 2016). "At 4 h of infection, EHEC partially inhibited TNF-α-induced p65 phosphorylation and EGF-induced ERK1/2 phosphorylation, while a complete inhibition of both pathways was observed by EPEC infection." (PMID 27774437, 2016). "The pro-inflammatory gene expression of CXCL10, TNF-α, and IFN-γ in the CNS and muscle tissues were up-regulated in the PBS group upon infection with EV71 5746 (C2) or 3340 (C4)." (PMID 26287531, 2015). "In contrast, the expression level of CXCL10, TNF-α, and IFN-γ were significantly lower in the mice vaccinated with either AlPO4- or AddaVAX-EV71 vaccines upon infection with EV71 5746 (C2) or 3340 (C4)." (PMID 26287531, 2015). "We also used qRT-PCR to analyze the effect of MOI on the induction of TNF-α and found that the induction of TNF-α by HCV was slight at 2 hours but significant (~10-fold) at 24 hours post-infection when the MOI used was 0.25." (PMID 26023919, 2015). "IDO can be induced in most human cells, especially antigen-presenting cells (APCs), by inflammatory cytokines such as interferon gamma (IFNγ), tumor necrosis factor (TNF)-α, and infection." (PMID 26579709, 2015). "Infection of the mouse RAW G9 cells with B. cenocepacia also led to activation of the stably expressed NF-κB and TNF-α reporters." (PMID 25831078, 2015). "The progress of chronic inflammation is driven by an amplified systemic occurrence of several proinflammatory cytokines, like tumor necrosis factor-α (TNF-α) and interleukin-1β (IL-1β), which are produced in response to infection and other cellular stresses." (PMID 26307982, 2015). "Macrophage activation up-regulated TNF-α and IL-6 and down-regulated IL-10 production upon PAO1-L infection and differences between the effects of IFN-γ and GM-CSF were observed." (PMID 25706389, 2015). "CD4 Th1 immunity is critical to sustain residual CD8 T-cell activity to control infection during persistent infection and is characterized in CD4 T cells by the secretion of IFN-γ, TNF-α, and IL-2." (PMID 26322025, 2015). "In this study, primers for quantitative real time PCR for Saimiri IFNγ, TNFα, IL2, IL6, IL10, and IL12 were validated and used in a study of splenic responses in S. sciureus during blood infection by P. falciparum." (PMID 25890318, 2015). "CCR6 is also one of the characteristics for a specific population of memory cells that secrete TNF-α, IL-2, and IFN-γ upon infection." (PMID 25894562, 2015). "Antiretroviral therapy promotes significant increases of IL-2+IFN-γ+- and IL-2+TNF-α+- secreting CD4+ T cells and hinders the progression from infection to active TB, while single IFN-γ+ CD4+ T cells declined significantly." (PMID 25822536, 2015). "The cross-reactive T cells during acute secondary infection have an altered cytokine responses consisting of low interferon gamma (IFN-γ) and high tumor necrosis factor alpha (TNF-α)." (PMID 26065421, 2015). "Compared to mock infected pigs, we found a significant downregulation of TNF-α and IFN-α in follicular and interfollicular areas of the mediastinal lymph node from 3 days post-infection (dpi) in animals infected with all three strains." (PMID 25889072, 2015). "To compare the functionality of CD39high and CD39int virus-specific CD8+ T cells, we isolated CD8+ T cells from mice with chronic infection at d35 post-infection and stained for IFN-γ and TNFα following in vitro stimulation with GP33-41 peptide." (PMID 26485519, 2015). "Higher levels of inflammatory cytokines, including IL-6, IFN-γ, TNF-α and MCP-1, were released in the livers of BG-exposed and unexposed malnourished mice 3 days post-infection compared with control, infected mice." (PMID 26241678, 2015).
infection (continued). "In this study, differences in TNF- α, CXCL1/KC, and lung histology were compared between CFTR–/– mice and WT-mice after 24 hours of infection with highly mucoid Sp strain CHB756." (PMID 26469863, 2015). "While no change was observed in the frequency of CD4+TNF-alpha+ T cells after 72 hours of infection with either T. cruzi strain, our data showed an increase in the frequency of CD8+TNF-alpha+ T lymphocytes." (PMID 26147698, 2015). "Most of the ISGs and cytokines, including IFNβ, IFIT2, TNFα, and IL6 were detected two hours post-infection." (PMID 25728279, 2015). "The results showed significant reductions in TNF-α, IL-1, IL-6, MCP-1, RANTES, and IFN-α in the MJWQH treated mice on day 4 after infection." (PMID 26089947, 2015). "TLR9−/− mice showed the same level of H. pylori colonization; however, the myeloperoxidase (MPO) activity and mRNA expression of TNF-α and IFN-γ were increased in the gastric tissue during the initial phase of infection." (PMID 25945326, 2015). "From these data we conclude that TNF and TNFR1 are both essential for controlling an infection with L. major, whereas TNFR2 only plays a contributory role." (PMID 26834705, 2015). "In parallel with decreased lung monocyte infiltration, SSa treatment attenuated PR8-induced IL-6 production in the lungs at all time points studied and attenuated TNF-α production from days 2 and 4 following PR8 infection." (PMID 26637810, 2015). "Specifically, cytokines and chemokines including IL-6, IL-8, TNF-α, as well as CCL-5, MIP-3α, and IP-10 were significantly induced, providing an immunopathological basis for liver pathology, deteriorated by infection-induced apoptosis." (PMID 26134299, 2015). "With increased time of infection, the expression of M1-type molecular markers such as CXCL11 and TNF-α significantly decreased, with the exception of CD86, which showed no significant change." (PMID 26091535, 2015). "The results showed that MJWQH significantly increased the survival rate of H1N1-infected mice and suppressed the production of TNF-α, IL-1, IL-6, MCP-1, RANTES, and IFN-α on day 4 after infection." (PMID 26089947, 2015). "As expected infection of bone marrow derived macrophage (BMDM) cells from C57/BL6 mice with MCMV triggered expression of the host pro-inflammatory cytokines IFNβ, IL6 and TNF." (PMID 25856589, 2015). "Serum total superoxide dismutase (SOD) activity, malondialdehyde (MDA) level, tumor necrosis factor alpha (TNF-α), C-reactive protein (CRP) and interleukin-1 beta (IL-1β) levels were measured at 5, 10, 15, 20 days post infection (dpi)." (PMID 25723390, 2015). "Primary wt AMs exposed ex vivo to RSV at different multiplicities of infection (MOI) produced IFN-α, IL-6 and TNF-α." (PMID 26688048, 2015). "We therefore considered it of interest to examine the impact of MyD88 deficiency on the concentrations of proinflammatory cytokines (TNF-α, IL-1β, IL-6) and CXC chemokines (KC, MIP-2) after infection with D39 or D39Δcps." (PMID 25700108, 2015). "We observed a significant down-regulation of TNF-α, IL-1β, IL-6 and IFN-γ, compared with the infection control, by ELISA and qPCR." (PMID 26405764, 2015). "Tumor necrosis factor (TNF) is a fascinating anti-tumoral cytokine, which plays a key role in orchestrating the fight of innate immunity against infection." (PMID 26071594, 2015). "With increased time of infection, the expression of M1 macrophage-related markers, including CD86, CXCL11, and TNF-α decreased, while the expression of M2 macrophage-related markers including CD206, CCL17 and IL-10 gradually increased." (PMID 26091535, 2015). "In agreement with Brégnard, we and others have previously demonstrated that HIV can become directly silenced following infection events as evidenced by enhancement of frequency of EGFP(+) cells following stimulation with anti-CD3/CD28, SAHA, or TNF-α." (PMID 26559763, 2015).
infection (continued). "As the infection became chronic, macrophages from infected MGL1−/− mice produced decreased levels of TNF-α, and the NO levels dropped significantly in both groups, but even more in MGL1−/− macrophages." (PMID 25664320, 2015). "Peritoneal infection by Enterococcus faecium is sensed predominantly by macrophages via TLR2 which then secrete IL6, TNF-α, MIP-2, and KC during early infection." (PMID 26172831, 2015). "Kinetics of production of individual cytokines varied: TNF-α was secreted early after infection while other cytokines (IL-10, IL-13, IFN-γ) became detectable 24 to 48 hours post-infection." (PMID 26024228, 2015). "Following the infection of SW480 cells, the mRNA levels of TLR2 and TNF-α increased gradually from 6 h, peaked at 48 h, and then decreased gradually." (PMID 25435993, 2015). "WNV-induced expression of pro-inflammatory cytokines such as IL-1β and TNF modulate BBB permeability, facilitate leukocyte trafficking into the brain, activate glial cells, and mediate neuronal death after infection." (PMID 26392176, 2015). "Mast cell derived LTB4 and granule proteases increase vascular permeability, while the synthesis and release of TNF-α, IL-6, IFN-α, CCL2, CCL3, CCL5, and CX3CL1 recruit NK cells and T cells to the site of infection." (PMID 26042121, 2015). "To validate transcriptional changes in iHOs after infection with S. Typhimurium SL1344, we carried out further microinjections with PBS or SL1344 and measured the mRNAs for IL-8, IL1B, IL23A, TNF, and CXCL2 with quantitative assays." (PMID 25964470, 2015). "At 2h after infection we identified significantly increased serum levels of MIP-1β, MCP-1, TNF-α and MIP-1α in hu-C4BPxFH compared to wt mice." (PMID 26200783, 2015). "The local innate immune response of mammary glands was swiftly activated after S. aureus inoculation during the initial stage of infection, characterized by up-regulation of gene expression of TLR2, NOD2, TNF-α, IL-1β, IL-6, and CXCL1." (PMID 25990971, 2015). "Levels of TNF-α at MGAS6180 infection sites were 2.27-, 5.8-, 9.9-, and 5.3-fold higher than those at MGAS315 infection sites at 8, 12, 16, and 24 h after GAS inoculation, respectively." (PMID 26047469, 2015). "Over-expression of CEACAM6 in intestinal cells has been reported after stimulation with inflammatory cytokines such as Interferon (IFN)-γ and Tumor Necrosis Factor (TNF)-α, or after infection with E. coli AIEC." (PMID 25706391, 2015). "In the case of T. cruzi, experimental infection induces NO production and suggests that IFN-γ and TNF-α are involved in the phenomenon." (PMID 25072046, 2014). "On day 8 post-infection, PbT-I cells were recovered from the spleen and briefly restimulated with anti-CD3 mAb to test for production of IFNγ, TNFα and CD107a, the latter of which is a surrogate marker for degranulation." (PMID 24854165, 2014). "At euthanasia, spleen MC of the infection group had produced significantly less IFN-γ, TNF-α, IL-1β, IL-6, IL-8 and IL-12p40 than MC of the other groups." (PMID 25252649, 2014). "Infection of BMMφ, TLR2/6 activation or treatment with TNF, all led to an increase of Camp mRNA levels." (PMID 25400920, 2014). "In RAW 264.7 cells the suppression of TNFα, MCP1, RANTES, and G-CSF production at both 3 and 6 h post infection was primarily due to the JNK inhibitor." (PMID 25166426, 2014). "Infection of macrophages with GP63+/+ or GP63−/− parasites revealed that Syt XI is degraded by GP63, leading to the release of TNF and IL-6." (PMID 25339958, 2014). "We measured concentrations of TNF-α, IFN-γ, MCP-1, IL-6, IL-10 and IL-12p70 in plasma of Asc−/−, Nlrp3−/− and WT mice 2 and 5 days after infection." (PMID 25115174, 2014). "Other studies using il10 knockout mice showed that these animals have a more efficient control over the infection by T. cruzi, reducing parasitism levels with a significant increase in the secretion of IFN-γ, TNF-α, IL-12, and NO." (PMID 25050370, 2014).
infection (continued). "The mRNA levels of IFN-gamma, IFN-alpha, IL-1, CCL20 and TNF in PBMC were variably affected by the primary Ad5hr infection, but IL-1, CCL20 and TNF were significantly decreased after subsequent Ad5 exposures." (PMID 25203111, 2014). "The mRNA and protein expression of TNF-α and IL-6 were increased significantly in BMDM after Mmass R morphotype infection, compared with those with S morphotype infection." (PMID 24402617, 2014). "In comparison, splenocytes of infected/p47phox−/− mice (± TcL) exhibited a mixed response with a predominance of IL-10 (IL-10>TNF-α>IFN-γ) at 7, 14, 21 and 30 days post-infection." (PMID 25474113, 2014). "Expression of CXCL9 and 10 can be induced by IFN-γ and/or TNFα in several liver resident cells, including hepatocytes, LSECs, HSCs and KCs, promoting further recruitment of CXCR3-expressing cells to the site of infection." (PMID 24646914, 2014). "An expansion of CD38+ CD69+ T cells in the acute phase compared to the resolving phase of infection with an increased in mRNA expression of IFN-gamma, TNF-α and IL-4 has reflected an increment in CD3+ CD38+ CD69+ T cells." (PMID 24963498, 2014). "Cases with congenital malformation, ascending infection, and perinatal anoxia showed increased IL-6, CRP, and TNF-α, respectively." (PMID 24659848, 2014). "This locus, Qivr6.1, is associated significantly (P-genome wide <0.05) with the amount of TNFα (peak LRS =25) and IFN-α (peak LRS =27) produced 48 hours after intranasal infection with HK213." (PMID 25418976, 2014). "It has been reported that an exacerbated inflammatory response in this sort of infection, involving proinflammatory cytokines such as IL-12, IFN-γ and, particularly, TNF-α, contribute not only to control the infection but also to damage the host tissue." (PMID 24991553, 2014). "In our study, we found that immunization with pcDNA-mGMCSF-Pxn1 induced the highest frequency of IFN-γ+TNF-α+IL-2+ CD4+ T cells and showed the highest level of protection of mice from L. major challenge infection." (PMID 25500571, 2014). "Quantitative PCR data revealed that MRSA-infection predominantly induced expression of TLRs 1, 2, 6, NR4A2, and inflammatory cytokines IL-8, IL-6, TNFα in hMSCs." (PMID 24661536, 2014). "We evaluated the levels of TNF-α, IFN-γ, IL-1β, and IL-6 in the hepatic tissue of untreated or EtOH-treated mice and uninfected or infected with Ab at 24, 48, and 72 h post-infection." (PMID 24752133, 2014). "Here, we found that mouse cathelicidin (Camp) expression was induced in bone marrow-derived macrophages by infection with Mycobacterium avium in a TLR2- and TNF-dependent manner." (PMID 25400920, 2014). "Although RRV-induced IL-6, TNF-α and CCL2 were lower in the OA hOBs compared to infected controls during early infection, the expression of these osteotropic factors in OA hOBs, with the exception of TNF-α, was significantly elevated at 96 hpi." (PMID 25407789, 2014). "The transient increases of pulmonary TNF-α 2 days post infection for BJ501 and of INF-γ and IL-10 at 6 days post infection for PR8 were observed." (PMID 24725777, 2014). "This study provided some basic data on the optimal time to observe different immune parameters, for example, IL-2+, IL-4+ CSCs stimulated about 12 days post infection, TNF-α, IFN-γ, IL-10 cytokines only transiently increased in the early infection." (PMID 24725777, 2014). "Expression level of TNF-α in the lung of VK627 and rVK627E infection groups were very significantly higher than the control (P < 0.01)." (PMID 25547136, 2014). "IL-1β, TNFα, MCP-1 and IL-8 mRNA are increasingly expressed in hepatocytes as early as 6 h after infection with H. hepaticus." (PMID 24932686, 2014). "Both VK627 and rVK627E infection can active the expression of NLRP3, IL-1β and TNF-α in the lung and brain of BALB/c mice at different levels and this also improved that site 627 in PB2 takes part in the virulence of H9N2." (PMID 25547136, 2014).
infection (continued). "Expression level of TNF-α in the control was very significantly lower than VK627 and rVK627E infection group at all days detected (P < 0.01)." (PMID 25547136, 2014). "Specifically, at both days 3 and 6 post-infection, IFNG, IL6, TNF, MIP1B and IL10 were all significantly diminished in MYD88-deficient mice as compared to wild-type mice." (PMID 25192715, 2014). "There was a relative decrease in the mRNA expression for TNF-α, IFN-κ, IFI16, IFIT1, MDA5, and RIG-I in the CPV-2 infected keratinocytes when compared to uninfected keratinocytes at 4 days post infection." (PMID 25025687, 2014). "In infected groups, the expression level of NLRP3, IL-1β and TNF-α increased rapidly at 3 dpi and VK627 infection were higher than that of rVK627E." (PMID 25547136, 2014). "TNF, IL-6, MIP-2, KC and MCP-1 were all highly expressed in response to infection in Camp −/− mice at 6 hours, and resolving by 24 hours, but were not significantly different from the responses quantified in infected wild type mice." (PMID 24887410, 2014). "In contrast, infection with ECTV and ECTV-Δ005 prevented transcriptional upregulation of TNFα, IL-1β, and IL-6." (PMID 25122471, 2014). "Liver NK cells have a protective role during the initial hepatic stage of infection by production of the TH1-type cytokines IFN-γ and TNF-α." (PMID 24498110, 2014). "In agreement with recent studies, which have identified a significant risk for non-serious and serious infections for even low-dose CS (< 10 mg/day of prednisone) the current study confirms that they are pro-infective and thus likely immunosuppressive, especially if combined with anti-TNFα." (PMID 24655394, 2014). "During the infection, high levels of IL-6 were detected in the serum of TS mice and TR mice presented high amounts of IFN-γ and TNF-α." (PMID 25437299, 2014). "Taken together, these results indicate that clearance of infection is dependent on a combination of innate immune responses mediated by IFN-γ, IL-12, TNF-α and other Th1 type cytokines." (PMID 25333720, 2014). "To test this, we treated Jurkat cells with TNFα (NFκB signaling agonist), BMS-345541 (IκB kinase inhibitor), SAHA (HDAC inhibitor) or DMSO (control) during RGH infection." (PMID 24502247, 2014). "Parasite numbers were counted in blood and skeletal muscle at different times post-infection, and real time-PCR expression levels of the cytokines IL-12, IL-4, IL-10, IFN-γ, and TNF-α were evaluated." (PMID 24991553, 2014). "Our results show that TNF also increased the infection rate of LCs with X4 HIV-1 and infection was blocked by AZT." (PMID 24990163, 2014). "Primary Ad5hr infection suppressed CCL20, TNF and IL-1 mRNA expression in PBMC, and subsequent virus exposures further dampened expression of these pro-inflammatory cytokines." (PMID 25203111, 2014). "A rapid increase of TNFα production was observed in TLR9-/- AMs compared to WT AMs, at both 2 and 4 hours post-infection." (PMID 24595157, 2014). "IAV infection significantly increased the levels of all tested proinflammatory cytokines (IL-1β, IL-6, IL-2, TNF-α, IFN-α, IFN-β and IFN-γ) in lung homogenates between 1.2- and 13.7-fold relative to the baseline (before infection)." (PMID 24865588, 2014). "In the early infection, the CD4+ T cell can release IFN-γ, IL-2, and TNF-α, which can activate macrophages to fight against M. tuberculosis." (PMID 24741595, 2014). "On other hand, monocyte and neutrophil recruitment, through KCs derived IL-6, IL-12, IL-1β, TNF-α, NO and chemokines (MIP-1α/β, MCP-1, MIP-2) limits the infection." (PMID 24976841, 2014). "Proinflammatory cytokines, including TNF-α, IFN-γ and IL-6, have an important role not only in immune responses against infection but also in pathological inflammation." (PMID 24587010, 2014). "Both IL-1β and TNF-α increased HCVpp (strain H77) infection of polarized HepG2.CD81 cells, whereas IFN-γ reduced infection in a dose-dependent manner." (PMID 24259385, 2014).